TREX1 (three prime repair exonuclease 1)
Diseases named in the same sentence as TREX1 in open-access papers (continued):
Sharing a sentence is not in itself a finding about the gene and the disease.
migraine (6 papers, 2016 to 2025). "TREX1-deficient brain cells exhibit neuroinflammatory and neurotoxic effects, a critical factor in the pathophysiology of migraine." (PMID 37592229, 2023). "In terms of genetic markers, mutations in CACNA1A, ATP1A2, and SCN1A are closely associated with FHM, while variants in NOTCH3 and TREX1 genes have been linked to migraine and its associated cerebrovascular diseases (e.g., cerebral arteriolar dominant disorders)." (PMID 39958329, 2025). "In human neural cells, deficiency of TREX1 contributes to the accumulation of extranuclear DNA, thereby inducing neurotoxicity through increased type I interferon secretion, which may play a role in the etiology of migraine." (PMID 37306871, 2023). "TREX1, shared by migraine and eGFR, and expressed in the brain, artery, spleen, and many other tissues, encodes a 3’ to 5’ DNA exonuclease known to regulate immunity and repair DNA." (PMID 37306871, 2023). "Through our analysis of two different brain proteomes using PWAS and TWAS of brain and vascular transcriptomes, we identified three potential causal genes for migraine (STAT6, ICA1L, and TREX1)." (PMID 37592229, 2023). "Among these genes, TREX1 remained significant using CMC brain tissues, previously reported to associate with migraine." (PMID 37306871, 2023). "Some genes such as CACNA1A, NOTCH3, TREX1 and COL4A1 are associated with nystagmus or vasculopathies related to migraines." (PMID 37622929, 2023). "While, four of these (ICA1L, TREX1, STAT6, and UFL1) have been previously reported in association with migraine." (PMID 37592229, 2023). "For kidney function, 19 significant tissue–gene pairs were found for migraine and eGFR using GTEx tissues, including four genes (TREX1, SHISA5, PRR13, TMA7) mainly expressed in tissues of the nervous and cardiovascular system." (PMID 37306871, 2023). "Therefore, TREX1 may play a significant role in the initiation and maintenance of migraine episodes, potentially through the modulation of neuroinflammatory processes." (PMID 37592229, 2023). "Five genes, including ICA1L, TREX1, STAT6, UFL1, and B3GNT8, showed significant correlation with migraine in both the proteome and transcriptome." (PMID 37592229, 2023). "To date, little is known regarding the exact biological functions of TREX1 and ICA1L in migraine and kidney function, and future functional studies are worth revealing their roles." (PMID 37306871, 2023).
microcephaly (5 papers, 2020 to 2023). A congenital or acquired developmental disorder in which the circumference of the head is smaller than normal for the person's age and sex. "These TREX1 mutations have been reported to associate with microcephaly, chilblains-like lesions, severe tetraparesis, cerebral calcifications, leukodystrophy, and raised cerebrospinal fluid IFNα, all typical clinical features of AGS." (PMID 35262626, 2022). "AGS is a rare autosomal recessive encephalopathy as a likely result of mutations in three-prime repair exonuclease 1 (TREX1), characterized by acquired microcephaly, cerebral calcification, leukodystrophy, and cerebral atrophy." (PMID 34332630, 2021). "Individuals with microcephaly or TREX1-related AGS, such as Case 1, were the most severely affected and less likely to achieve normal developmental milestone." (PMID 35964089, 2022). "AGS caused by mutations in TREX1, RNASEH2A, and RNASEH2C usually presents early in the neonatal period as “pseudo-TORCH” manifestations with severe neurological dysfunction in the form of progressive microcephaly, spasticity, psychomotor retardation, and may lead to death." (PMID 32737687, 2020).
Sjögren’s syndrome (5 papers, 2013 to 2025). "Polymorphisms in the TREX1 gene were associated with autoimmune manifestations, such as systemic lupus erythematosus and Sjögren’s syndrome, and with retrovirus infection." (PMID 38675842, 2024).
cardiomyopathy (4 papers, 2017 to 2024). A disease of the heart muscle or myocardium proper. "Trex1–/– mice develop a lethal disease within a few months after birth due to severe inflammation including cardiomyopathy." (PMID 39254994, 2024).
hepatocellular carcinoma (4 papers, 2021 to 2025). A malignant tumor that arises from hepatocytes. "Of note, two hepatocellular carcinoma samples in TCGA carried the L44P TREX1b protein sequence variant, while organoids from two gastric adenocarcinoma patients carried the C99R variant, suggesting a possibility of associations of specific TREX1 variants with specific tumor histologies." (PMID 40581636, 2025). "Of note, L44P occurred in two hepatocellular carcinoma samples in TCGA (LIHC).We modeled TREX1 mutations occurring in human tumors to evaluate predicted impact on protein stability and function using structure-based approaches FoldX and INPS-3D." (PMID 40581636, 2025). "Indeed, TREX1 appears to be upregulated in different tumor entities, including cervical, breast, and hepatocellular cancer, making TREX1 an attractive target in tumor therapy, whose inactivation is thought to increase cancer cell immunogenicity." (PMID 40098954, 2025).
leukodystrophy (4 papers, 2018 to 2024). Leukodystrophies are a group of rare, progressive, metabolic, genetic diseases that affect the brain, spinal cord and often the peripheral nerves. "Radiographic features of AGS patients have uncovered leukodystrophy symptoms such as white matter rarefaction, deep white matter cysts, and inadequate myelination in patients with TREX1 mutations." (PMID 38129659, 2024). "In this study, we combined TREX1-KO microglia with control organoids and discovered that TREX1-KO microglia disrupts the oligodendrocyte lineage, suggesting that AGS leukodystrophy may be caused by microglia." (PMID 38129659, 2024).
Nephropathy (4 papers, 2012 to 2024). A nonspecific term referring to disease or damage of the kidneys. "Hereditary endotheliopathy with retinopathy, nephropathy, and stroke (HERNS) is a rare multisystemic disease presenting with leukoencephalopathy, progressive visual loss and nephropathy due to mutations in the TREX1 gene." (PMID 22436252, 2012). "Heterozygous frameshift mutations in TREX1 (three prime repair exonuclease 1) were also be involved in vascular dysfunctions, and caused cerebroretinal vasculopathy or hereditary endotheliopathy, retinopathy, nephropathy and stroke." (PMID 31484286, 2019). "Trex1−/− rats also gradually develop diabetic complications, such as cataracts and nephropathy, after onset of diabetes." (PMID 38166933, 2024).
osteosarcoma (4 papers, 2016 to 2022). A usually aggressive malignant bone-forming mesenchymal neoplasm, predominantly affecting adolescents and young adults. "Another study showed that knockdown of the three prime repair exonuclease 1 (TREX1) enhanced stemmness properties and resistance to cisplatin and doxorubicin in osteosarcoma cells through the E2F4-mediated activation of the Wnt/β-catenin pathway." (PMID 34198693, 2021). "An additional study reported that TREX1 (three prime repair exonuclease 1) negatively regulates the self-renewal of osteosarcoma CSCs." (PMID 34476219, 2021). "The expression of TREX1 protein in patients with osteosarcoma in the metastasis group was significantly lower than that in the non-metastasis group." (PMID 27881153, 2016). "The expression of TREX1 was positively related to the prognosis of patients with osteosarcoma, namely the higher the expression of TREX1 was, the longer the patients’ survival time." (PMID 27881153, 2016). "The study aimed to explore the correlation between the expression of TREX1 and the metastasis and the survival time of patients with osteosarcoma as well as biological characteristics of osteosarcoma cells for the prognosis judgment of osteosarcoma." (PMID 27881153, 2016). "The expression of TREX1 was closely related to the cytobiology characteristics of osteosarcoma stem cell." (PMID 27881153, 2016). "The single factor analysis of 45 patients with osteosarcoma showed that the expression of TREX1 was an independent factor affecting the patients’ prognosis (P < 0.05)." (PMID 27881153, 2016). "The correlation between the expression of TREX1 protein and the occurrence of pulmonary metastasis in 45 cases of osteosarcoma was analyzed." (PMID 27881153, 2016). "The TREX1 protein observed in cytoplasm was faint yellow granular in the osteosarcoma tissue of the metastasis group, scatteredly distributed." (PMID 27881153, 2016). "TREX1 protein was lowly expressed in 21 cases of patients in the metastasis group, suggesting that the expression of TREX1 was closely related to the lung metastasis in osteosarcoma." (PMID 27881153, 2016). "Therefore, the expression of TREX1 can be used as an effective index to jugde the prognosis of patients with osteosarcoma." (PMID 27881153, 2016). "However, it was unclear whether the expression of TREX1 was related to the occurrence, development, and metastasis of osteosarcoma." (PMID 27881153, 2016). "Thus, the expression of TREX1 was closely related to the drug resistance, relapse and metastasis of osteosarcoma stem cells, and the expression of TREX1 could indicate the prognosis of osteosarcoma." (PMID 27881153, 2016). "The expression of TREX1 may be related to metastasis in patients with osteosarcoma." (PMID 27881153, 2016). "Low expression of TREX1 and resistance to cisplatin in CD133+ cells were observed indicating TREX1 gene was related to the drug resistance of osteosarcoma, which was consistent with the previous report." (PMID 27881153, 2016). "TREX1 protein was expressed in the cytoplasm and nucleus in the osteosarcoma tissues of the non-metastasis group." (PMID 27881153, 2016). "The analysis by IPP6.0 software showed that the positive rate of the non-metastasis group was high, the positive intensity was strong and the difference was statistically significant (P < 0.05), suggesting that TREX1 protein was highly expressed in the osteosarcoma in the non-metastasis group." (PMID 27881153, 2016).
Retinal Vasculopathy with Cerebral Leukodystrophy (4 papers, 2016 to 2025). "TREX1 mutations that cause Retinal Vasculopathy with Cerebral Leukodystrophy (RVCL) exhibit dominant inheritance and are exclusively frame-shift mutations in the C-terminal tail region of the enzyme." (PMID 33868310, 2021).
cerebral small vessel disease (3 papers, 2021 to 2023). Cerebral small vessel disease is the term currently used to pathological processes that affect the brain parenchymal circulation (arterioles, capillaries, and veins). "For patients carrying variants outside EGFr region, no potential pathogenic mutation were identified in several other genes known to be common causal of cerebral small-vessel disease or vascular dementia (HTRA1, TREX1, COL4A1, COL4A2, GLA, APP, and ITM2B) by targeted next-generation sequencing." (PMID 34335700, 2021).
developmental delay (3 papers, 2023 to 2025). "In this study, we identified two homozygous mutations in the TREX1 gene (c.-26-1G>A and c.-26-95G>T, based on NM_033629.6) in two Inuit siblings from the Sanikiluaq region of North of Quebec, presenting with severe developmental delay, neurodegeneration, and systemic inflammation." (PMID 40061936, 2025).
lung adenocarcinoma (3 papers, 2017 to 2024). A carcinoma that arises from the lung and is characterized by the presence of malignant glandular epithelial cells. "Under the same physical dosage, it was investigated how various LET rays affected the upstream regulatory factors TREX1, IFNB1, important marker of immunogenic death, and PD-L1 in Lewis lung adenocarcinoma cells." (PMID 38495488, 2024).
multiple sclerosis (3 papers, 2018 to 2024). A progressive autoimmune disorder affecting the central nervous system resulting in demyelination. "Strikingly, polymorphisms in TRIM5, TRIM22, and BST2, but not APOBECs or TREX1 were significantly associated to another neuroinflammatory disorder, multiple sclerosis." (PMID 29872426, 2018).
non-Hodgkin lymphoma (3 papers, 2020 to 2025). Distinct from Hodgkin lymphoma both morphologically and biologically, non-Hodgkin lymphoma (NHL) is characterized by the absence of Reed-Sternberg cells, can occur at any age, and usually presents as a localized or generalized lymphadenopathy associated with fever and weight loss. "On this basis, genetic variants of genes implicated in the regulation of chronic inflammation such as TNFAIP3 –, and LILRA3, B cell activation, type I IFN pathways such as TREX-1 as well as epigenetic processes have been shown to increase the risk of Non-Hodgkin Lymphoma (NHL) in SS." (PMID 35402956, 2020).
Obesity (3 papers, 2018 to 2024). Accumulation of substantial excess body fat. "Downregulation of DNase2 and TREX1 is also observed in HSCs in the obesity-associated liver tumor microenvironment in vivo, and the blockade of this pathway prevented SASP in HSCs and obesity-associated hepatocellular carcinoma development in mice." (PMID 35365245, 2022). "Using this obesity mouse model, we found that the expression levels of both DNase2 and TREX1 in HSCs (which express Desmin) were substantially reduced in obese mice fed a high-fat diet (HFD), as compared to those in lean mice fed a normal diet (ND)." (PMID 29593264, 2018).
small cell lung carcinoma (3 papers, 2024 to 2025). Small cell lung cancer (SCLC) is a highly aggressive malignant neoplasm, accounting for 10-15% of lung cancer cases, characterized byrapid growth, and early metastasis. "Similarly, elevated TREX1 levels have been observed in drug-resistant small-cell lung cancer, potentially facilitating the survival of therapy-resistant tumor cells." (PMID 41346575, 2025).
Stroke (3 papers, 2018 to 2022). Sudden impairment of blood flow to a part of the brain due to occlusion or rupture of an artery to the brain. "In the cerebellum, an association of TREX1+ cells with the dentate nucleus was observed in all stroke cases (n=4), similar to our findings in normal controls." (PMID 30062819, 2018). "Cognitive features were the most common clinical cerebral phenotype for 4 of 7 genes (HTRA1HomZ, COL4A2, HTRA1HetZ, and CTSA); stroke was the most common among individuals with COL4A1 and ADA2, and headache was most common among individuals with TREX1." (PMID 35699195, 2022). "The number of TREX1+ microglia was increased in ischemic brain lesions in central nervous system of RVCL and stroke patients." (PMID 30062819, 2018).
triple-negative breast carcinoma (3 papers, 2023 to 2025). An invasive breast carcinoma which is negative for expression of estrogen receptor (ER), progesterone receptor (PR), and human epidermal growth factor receptor 2 (HER2). "STING-independent, DDX3X-mediated cytosolic DNA sensing and immune activation in TREX1-deficient triple negative breast cancer cells has also been reported." (PMID 40581636, 2025). "In this study the authors genetically silenced TREX1 in triple negative breast cancer cells to increase levels of ssDNA and then evaluated promotion of tumor immunogenicity in response to ssDNA accumulation." (PMID 39178223, 2024). "Finally, our results show that one gene in the mismatch repair pathway (three prime repair exonuclease 1 = TREX1) was induced by PAC in triple-negative breast-cancer cells." (PMID 37298600, 2023).
CARASIL (2 papers, 2019 to 2022). CARASIL is a hereditary cerebral small vessel disease characterized by early-onset gait disturbances, premature scalp alopecia, ischemic stroke, acute mid to lower back pain and progressive cognitive disturbances leading to severe dementia. "A number of different genes come under the umbrella term of vascular leukoencephalopathies, including NOTCH3 (CADASIL), HTRA1 (cerebral autosomal recessive arteriopathy with subcortical infarcts and leukoencephalopathy (CARASIL)), CTSA (CARASAL), COL4A1 and TREX1." (PMID 30467211, 2019).
Cerebral atrophy (2 papers, 2021). Atrophy (wasting, decrease in size of cells or tissue) affecting the cerebrum. "Aicardi-Goutières (AGS) is a rare immune dysregulated disease due to mutations in TREX1, RNASEH2A, RNASEH2B, RNASEH2C, SAMHD1, ADAR1 or IFIH1, characterized by encephalopathy, dystonia, basal ganglia calcifications, white matter abnormalities, and cerebral atrophy." (PMID 33482855, 2021).
cerebrovascular disease (2 papers, 2022 to 2025). "Monoallelic TREX1 mutations were identified in patients showing early-onset cerebrovascular disease, ascribable to small vessel disease, and CADASIL-like neuroimaging." (PMID 35885962, 2022).
colon cancer (2 papers, 2024). "In breast and colon cancers, high expression of TREX1 leads to blockage of type I IFN pathway activation, inhibiting the anti-tumor immune response and the anti-tumor response of immune checkpoint inhibitors." (PMID 38835789, 2024).
congenital toxoplasmosis (2 papers, 2008 to 2017). Toxoplasma infection that is present from birth. "The recent finding that Aicardi-Goutieres's Syndrome is caused by mutations in a DNAase, TREX1, which leads to increased interferon-α production, suggests a possible similarity in pathogenesis of Aicardi-Goutieres's syndrome abnormalities and some of those in human congenital toxoplasmosis." (PMID 18947414, 2008). "Our sequential analysis of other candidate susceptibility loci presented herein, found that TREX1, TIRAP MAL, FOXQ, and TLR9 also had allelic variants significantly associated with susceptibility to congenital toxoplasmosis in the NCCCTS (p < 0.05)." (PMID 28904337, 2017).
COVID-19 (2 papers, 2022). A disease caused by infection with severe acute respiratory syndrome coronavirus 2. "This suggests that the remaining CpGs (annotated in genes such as CCDC61, CD38, FAM38A, LAT, TREX1 or NFAT5, among others) differentially contribute to similarities between COVID-19 progression and SADs, some of them regulating the activation and differentiation of T and B lymphocytes." (PMID 35933486, 2022).